TNF (tumor necrosis factor)
Diseases named in the same sentence as TNF in open-access papers (continued):
Sharing a sentence is not in itself a finding about the gene and the disease.
tumor (continued). "The rationale is based on the direct effects of TNF in destroying the tumour vasculature at high doses, and on its effects in stimulating antitumour immunity." (PMID 23326670, 2012). "CD8+ T cells treated with Cl-IB-MECA secrete TNF-α which is crucial for the observed anti-tumor effects in mice." (PMID 23028986, 2012). "CXCL12 can also promote TNFα expression, which can activate nuclear factor κB (NF-κB) and act back on tumour cells to induce cell surface CXRC4 expression." (PMID 22415233, 2012). "TNF-α also promotes tumour cell survival by inducing genes coding for NFκB dependent anti-apoptotic molecules." (PMID 23905066, 2012). "Numerous studies have focused on the use of the NGR motif for ligand-directed delivery of various drugs and particles to tumor vessels, such as tumor necrosis factor α (TNF α), doxorubicin, proapoptotic peptides, liposome and tissue factor." (PMID 22590653, 2012). "Although this specific cytokine is an important component of the initial immune response to infection with a pathogen, TNF is also known to promote tumor progression specifically in the context of chronic inflammation or in the presence of activated Ras." (PMID 23093933, 2012). "In a contradictory role to this, in low chronic doses, TNF-α promotes tumour growth, invasion, and metastasis." (PMID 22737166, 2012). "Two of the key molecules mediating the inflammatory processes in tumour promotion are cytokines tumour necrosis factor-α (TNF-a), and IL10." (PMID 22520842, 2012). "Komori’s group reported that human TNF-α is 1000 times more effective than the chemical tumour promoters okadaic acid and 12-O-tetradecanoylphorbol-13-acetate in inducing cancer." (PMID 23905066, 2012). "Previous reports have shown that the addition of TWEAK to several tumor cell lines results in an increased production of TNFα, which is responsible for the observed death phenomenon." (PMID 22438963, 2012). "IGROV1-Luc tumour cells in vitro secreted TNF-α, TNFR1-α, TGF-α, AREG, HB-EGF and IL-6Rα, all known substrates for the shedding activity of ADAM17, into the culture medium even when unstimulated." (PMID 22792380, 2012). "Deregulated TNF expression within the tumor microenvironment appears to favor malignant cell tissue invasion, migration, and ultimately metastasis formation." (PMID 23028877, 2012). "It has also been demonstrated that TNF-α increases intratumoural vessel permeability and reduces interstitial pressure, facilitating drug penetration in tumours." (PMID 22719951, 2012). "As previously discussed, TNF-α, a cytokine, can act as a tumour regressor in high doses where it functions as a vasculotoxic agent and as such is being researched as one of these cytotoxic enzymes." (PMID 22737166, 2012). "TNF-α is involved in all steps of tumour genesis, including cellular transformation, promotion, survival, proliferation, invasion, angiogenesis, and metastasis." (PMID 23905066, 2012). "SAA proteins are also chemotactic for other inflammatory cells such as mast cells and T lymphocytes, induce the expression of ECM remodeling enzymes, and stimulate production of inflammatory cytokines such as TNF-α that promote tumor growth." (PMID 22699312, 2012). "To test this assumption, we used differentiated L6 and C2C12 myotubes treated with TNF-α as in vitro models of muscle atrophy, and an in vivo mouse model of tumor-induced cachexia." (PMID 22257771, 2012). "Tax tumor cells express IL-6, M-CSF, IL-1, TNF-α, and Tax expression enhances IL-6 and TNF-α expression in vitro and in vivo." (PMID 21994759, 2011). "Pre-treatment of tumor cells or mice with TNF increases the metastatic activity of transplantable tumor cells." (PMID 24212934, 2011). "Combination with chemotherapy in the setting of hyperthermic isolated limb perfusion has proven quite successful, based not only on a direct anti-proliferative effect of TNF-α, but also due to its ability to increase drug penetration into tumor tissue." (PMID 22036896, 2011).
tumor (continued). "An immune response to the tumor resulting in activation of macrophages and the release of cytokines, such as tumor necrosis factor, IL-1, IL-6, and interferon-r, is central to the current model, as is the release of tumor by-products." (PMID 21896191, 2011). "CCL2, CCL5, TNFα and IL-1β were expressed at very low incidence in normal breast epithelial cells, but their incidence was significantly elevated in tumor cells of the three groups of cancer patients." (PMID 21486440, 2011). "We showed an increased expression of MCP-1, GM-CSF and TNF-α in the HR tumor cell line pulsed with IL-1β, both by flow cytometry and cytokine array analyses." (PMID 21978632, 2011). "TNF can induce the cell death of various tumor cells only in the presence of RNA synthesis inhibitors or protein synthesis inhibitors." (PMID 24212934, 2011). "TNF-α secretion can be induced by conserved structural elements common to microbial pathogens as well as by tumour cells." (PMID 22029602, 2011). "In support of the observations on JNK signalling, we also explored further the roles of IFN-γ and TNF-α in increasing HLA1 expression on tumours." (PMID 21829193, 2011). "Based on our findings, the possibility exists that different inflammatory mediators act in complementary manners at the tumor microenvironment to support processes of tumor growth and progression, with potentially major roles for TNFα." (PMID 21486440, 2011). "A high incidence of expression in the tumor cells was also denoted for TNFα and IL-1β in the three groups of cancer patients: DCIS, IDC-no-relapse and IDC-with-relapse." (PMID 21486440, 2011). "Intriguingly, Sugarman and colleagues showed that the cytostatic and cytotoxic effects of TNF-α were cell line specific, with only a proportion of tumor cell lines responding to TNF-α." (PMID 22036896, 2011). "We have previously shown that specific inhibition of TNF-alpha with Infliximab or Etanercept significantly reduces tumor recurrence, as determined by endpoint measurement of tumor weight and histological analyses." (PMID 21699694, 2011). "TNF-α and its related NF-κB transcription factor are described as critical components of tumor progression." (PMID 21754991, 2011). "Malaria infection in LLC-bearing mice also significantly increased the secretion of IFN-γ and TNF-α, the activation of NK cells, tumor-specific T-cell proliferation, and cytolytic activity of CD8+ T cells." (PMID 21931708, 2011). "While 131I-labeled SSLs alone retarded tumor growth, complete tumor regression and cures were only observed when they were used in combination with TNF-α." (PMID 21378416, 2011). "Collectively, these observations indicate the crucial contribution of intratumoral TNF-α to tumor neovascularization." (PMID 24212934, 2011). "TNF has been shown to induce tumor cell invasion through NF-κB- and JNK-mediated upregulation of migration-inhibitory factor in macrophages and through enhanced MMP production in tumor cells." (PMID 22162712, 2011). "Macrophages and other immune cells invading the tumor space, and tumor cells themselves, secrete TNF-α." (PMID 21880146, 2011). "Through the direct killing mediated by perforins and granzyme granules acting together with the apoptotic inducers, TNF-α and Fas, tumor cells were eliminated in EGF-SEA-treated mice, as demonstrated by TUNEL staining." (PMID 21311755, 2011). "The pathogenesis of tumor cachexia is still not fully understood but a multifactorial process including pro-inflammatory cytokines like IL-6 or TNF-α, neuroendocrine hormones, downregulation of IGF-1 and tumor proteolysis inducing factor is assumed." (PMID 21892933, 2011). "TNF-alpha and the tumour factor proteolysis-inducing factor are the major contenders for skeletal muscle atrophy in cachectic patient." (PMID 21760776, 2011). "These two drugs, particularly when used in combination, promote tumor cell apoptosis and down-regulate the expression IL-6, IL-8, and TNF-α cytokines." (PMID 21345194, 2011).
tumor (continued). "In vivo experiments using the combination of TNF-α and liposomal doxorubicin showed a significantly increased survival benefit in tumor-bearing mice treated with the combination in comparison to mice treated with either TNF-α or liposomal doxorubicin alone." (PMID 22036896, 2011). "The novel concept of using systemic TNF-α to facilitate increased tumor penetration of liposomal chemotherapy seems particularly promising and worth exploring clinically." (PMID 22036896, 2011). "The failure of IFNαA to inhibit tumor growth in our mouse models reinforces a need to consider alternate biotherapeutic strategies, such as TNFα or IL-24 that are known to have anti-angiogenic properties." (PMID 21401924, 2011). "Investigation of the interaction of TNF-α and radiation in 14 human tumor cells lines demonstrated synergistic or additive cytotoxicity with the maximum effect when TNF-α was given 4-12 hours before irradiation." (PMID 22036896, 2011). "Together, these findings indicate that there was high incidence of CCL2, CCL5, TNFα and IL-1β expression in the tumor cells in the three groups of cancer patients, and that the expression of TNFα and IL-1β was further elevated in the IDC-with-relapse group." (PMID 21486440, 2011). "Pro-inflammatory cytokines, such as TNF and IL-6, can influence all stages of tumor development, including initiation, promotion, progression and metastasis." (PMID 21943068, 2011). "The colloidal gold–TNF vector had lower toxicity and a higher efficacy in reducing tumor size in comparison with the native TNF, since maximum antitumor reaction was attained by using lower doses of the drug." (PMID 22649683, 2011). "After accumulation, the T cells stimulated by EGF-SEA became tumor-sensitive CTLs that secreted the tumoricidal cytokines TNF-α and IFN-γ, and the granulolytic proteins perforins and granzyme B." (PMID 21311755, 2011). "Pro-inflammatory cytokines, such as interleukins (ILs) and tumor necrosis factor-alpha (TNF-α), have been implicated in tumor promotion in various experimental models of tumorigenesis." (PMID 24212813, 2011). "One study of oesophagogastric cancers showed cytokine protein concentrations of IL-1β, IL-6 and TNF-α are significantly elevated in tumour tissue." (PMID 21760776, 2011). "FWGE was shown to upregulate the expression of ICAM-1 on tumor endothelial cells and to synergize these effects of tumor necrosis factor alpha." (PMID 21892933, 2011). "These networks show involvement of key players including TNF alpha, NFκB, c-myc, Her2/Neu, β-catenin, and Erk1/2 proteins, which regulate inflammation, and the survival and proliferation of tumor cells." (PMID 21305022, 2011). "Neutralizing antibodies to cytokines GM-CSF, IL-1β, IL-6, VEGF, or TNFα were tested in PBMC-tumor cell line co-cultures to determine which factor(s) was most important for induction." (PMID 21658270, 2011). "To investigate this possibility, we tested the ability of TNFα and IL-1β to induce in the tumor cells properties that are typical of EMT." (PMID 21486440, 2011). "As in the periphery, α4-1BB promoted the greatest increase in IFN-γ, TNF-α double producing CD8+ T-cells in the tumor." (PMID 21559358, 2011). "Prior to the discovery of TRAIL, two other members of the TNF family—the prototypic TNF and the closely related Fas Ligand (FasL)—had been identified as potent inducers of tumor cell death." (PMID 24212631, 2011). "When DC vaccine was pulsed with tumor antigens along with CT extract, the levels of TNF-α and IL-1β were dramatically increased with a dose-dependent response and more immunologic and co-stimulatory molecules were expressed on the DC surface." (PMID 19001481, 2011). "Anti-CRD4 MR scFv #G11 preserved CD206low macrophage phenotype during co-culture with tumor cells, as shown by the up-regulation of IL-12 (condition 4), TNF-α (conditions 4, 6), and IL-6 (conditions 4, 6)." (PMID 22163010, 2011).
tumor (continued). "When combined with TNF-α, however, a single administration of these agents led to complete tumor regression in all animals and long-term cures in more than 75% of them." (PMID 21378416, 2011). "TB mice had elevated levels of the procachectic cytokines TNFα (77.2%greater than C; P=0.02) and IL-6 (8,120.1% greater than C;P=0.01) 14 days after tumor implantation." (PMID 21069263, 2011). "Future directions for the development of TNF-α therapy rely on amelioration of the toxicity seen with systemic therapy and thereby increasing direct tumor response through higher TNF-α doses." (PMID 22036896, 2011). "TNF can inhibit the function of αvβ3 integrin, an adhesion molecule expressed on tumor endothelial cells and sever the interaction between endothelial cells and the surrounding extracellular matrix." (PMID 24212934, 2011). "TNF-α was originally described as an endotoxin-induced, macrophage-derived protein with different effects depending on the tumor type to which it is administered." (PMID 21625390, 2011). "The liberation of multiple proinflammatory cytokines, including interleukin-1 (IL-1), IL-6, and tumor necrosis factor-α from the tumor environment eventually results in the induction of CRP synthesis from the liver and other tissues." (PMID 22103888, 2011). "125I-labeled SSLs were intravenously injected into tumor-bearing mice in combination with either C. novyi-NT or TNF-α." (PMID 21378416, 2011). "While TNFα was found to have multiple tumor-promoting roles in this disease, there are malignant diseases in which it was described as an anti-malignancy factor." (PMID 21486440, 2011). "While HUVEC (macrovascular cells) have been largely used in the past, here, we documented an NF-κB gene signature in TNFα-stimulated microvascular endothelial cells HMEC often used in tumor angiogenesis studies." (PMID 21754991, 2011). "In contraposition, and again in both tumor cell lines treated with TNF-α or CIS, the phosphorylated fraction was drastically incremented (P < 0.001 vs CTL, PTX)." (PMID 22074157, 2011). "Taken together, the in vitro and in vivo data were suggestive that TNF-α had the potential to be highly specific anti-cancer therapy, with activity against a number of tumor types." (PMID 22036896, 2011). "When CT26 tumor-bearing mice were injected with murine TNF-α and radiolabeled murine IgG, significant IgG accumulation was observed in the tumors but not in the normal tissues." (PMID 21378416, 2011). "Further analyses indicated that TNFα has led to substantial decrease in the expression of β-catenin at the cell membrane of the tumor cells, an event which is typical of EMT." (PMID 21486440, 2011). "In vivo, TNF-α has shown activity against a wide variety of murine tumor types and human tumor xenografts." (PMID 22036896, 2011). "Most importantly, through its ability to up-regulate the expression of tumor promoting cytokines, such as IL-6 or TNF-α, and survival genes, such as Bcl-XL, NF-κB provides a critical link between inflammation and cancer." (PMID 21901145, 2011). "Asparagine-glycine-arginine conjugated to the N-terminus of TNF-α (NGR-TNF-α) specifically binds the aminopeptidase N (CD13) of tumor vasculature." (PMID 22036896, 2011). "Next, we determined serum levels of the proinflammatory and tumor-promoting cytokines, tumor necrosis factor alpha (TNF-α) and interleukin (IL)-6." (PMID 21725989, 2011). "TNFSF10 encodes the cytokine tumor necrosis factor-related apoptosis-inducing ligand (TRAIL) that binds to TNF and induces apoptosis, primarily in tumor cells." (PMID 21711548, 2011). "Accordingly, tumor cells co-cultured with macrophages display increased cell migration which is mediated through TNF-α which is released by macrophages." (PMID 21914164, 2011). "TNF was initially identified as a factor responsible for hemorrhagic necrosis in tumor tissues in mouse." (PMID 24212934, 2011).
tumor (continued). "TNF-α is highly expressed in tumors where it has been considered initially as a potent tumor cell killer and an anti-vascular cytokine at high doses." (PMID 21754991, 2011). "Interferons act alone or can synergize with TNFα to inhibit proliferation of endothelial cells and angiogenesis, and in this way act to prevent tumor development." (PMID 21401924, 2011). "When gene expression was analyzed with respect to tumor sizes, both immunosuppressive (CTLA4) and immune stimulatory (IFNγ and TNFα) genes were increased with increasing tumor size." (PMID 22013484, 2011). "It selectively causes the collapse of tumor vasculature leading to extensive cell death by altering tumor vascular permeability directly and indirectly, through the induction of various vasoactive mediators, such as TNF-α." (PMID 24212824, 2011). "At day 7, spinal TNF-α levels of tumor receiving thalidomide group (0.69 ± 0.06) was significantly decreased compared with that of tumor receiving vehicle group (1.28 ± 0.15)." (PMID 20923560, 2010). "In particular, we studied the production of Th1 cytokines, namely IFNγ and TNFα, which play an important role in anti-tumor immunity." (PMID 21092174, 2010). "TNFα expression was increased in the tumour islets of patients with above median survival (AMS) compared to those with below median survival (BMS)(p = 0.006), but similar in the stroma of both groups." (PMID 20573209, 2010). "A wide variety of evidence has pointed to a critical role of TNF-α in tumour proliferation, migration, invasion and angiogenesis." (PMID 20087353, 2010). "Expression of cytokines IL-10, TGF-β and TNF-α were increased during tumor growth whereas IFN-γ showed a decrease of the expression from day 10 on following an initial increase." (PMID 20205946, 2010). "Pro-inflammatory TNF-α released by host and tumor cells is an important factor involved in initiation, proliferation, angiogenesis as well as metastasis of various cancer types." (PMID 20051112, 2010). "TNFα, another macrophage-derived factor that can induce Wnt signaling in tumor cells, also elevated the levels of Snail in tumor cells." (PMID 20661477, 2010). "Proportionately more people in the DMARD comparison group than in the anti-TNF group died of a neoplasm (32% versus 20%)." (PMID 20662063, 2010). "Macrophages not only can serve as antigen-presenting cells (like mature dendritic cells), but also can serve as cytotoxic cells (like cytotoxic T cells) through releasing reactive oxygen/nitrogen intermediates and TNFα to kill the nearby tumor cells." (PMID 20487543, 2010). "Among various types of immune cells, CD8+ cytotoxic T cells are well known for their anti-tumor activity by directly killing transformed cells through the perforin-granzyme pathway and death ligand such as Fas and tumor-necrosis factor." (PMID 20961430, 2010). "The finding that TNFα is able to induce tumor cell apoptosis led it to be named TNF before its role in the inflammatory process was revealed." (PMID 20064207, 2010). "The p38-MAPKs are strongly activated by inflammatory cytokines and environmental stresses, and p38 is required for the expression of TNFα and interleukin-1 during tumor inflammatory responses." (PMID 20426862, 2010). "It has been demonstrated that primary tumors secrete soluble factors, including VEGF-A, TGFβ and TNFα, which induce expression of S100 in the myeloid and endothelial cells within the lung prior to tumor metastasis." (PMID 20497537, 2010). "Well known is the case of TNFα, produced by tumor and immune cells, which leads to the survival of cancer cells by the upregulation of antiapoptotic proteins, that is, Bcl-2, via the activation of the nuclear factor kappa B (NFκB)." (PMID 20339581, 2010). "At one end of the continuum are the classically activated M1 macrophages that produce effector molecules such as reactive oxygen intermediates, reactive nitrogen intermediates, and TNFα, to limit tumor growth." (PMID 20338029, 2010).